Y_RNA (Y RNA )
Gene: Miscellaneous RNA gene on chromosome 16 (30,453,997 to 30,454,097, reverse strand). Ensembl gene ENSG00000202476.
Homologues: Orthologues: chimpanzee Y_RNA (98% identical), guinea pig Y_RNA (91% identical), guinea pig Y_RNA (88% identical). Paralogues in human: RNY3 (89% identical), Y_RNA (89% identical), Y_RNA (88% identical), Y_RNA (87% identical), RNY3P1 (86% identical), Y_RNA (86% identical), RNY3P14 (85% identical), Y_RNA (85% identical), RNY3P11 (84% identical), Y_RNA (84% identical), Y_RNA (83% identical), RNY3P16 (82% identical), and 94 more.